ENSG00000257767 (novel protein)
Gene: Protein-coding gene on chromosome 12 (111,753,890 to 111,791,418, forward strand). Ensembl gene ENSG00000257767.
Genetic constraint (gnomAD): Loss-of-function variants: 23 observed, 29.9 expected, observed/expected ratio (o/e) 0.77, 90% interval 0.55 to 1.09. Missense variants: 303 observed, 376.31 expected, observed/expected ratio (o/e) 0.81, 90% interval 0.73 to 0.89. Synonymous variants: 133 observed, 146.17 expected, observed/expected ratio (o/e) 0.91, 90% interval 0.79 to 1.05.